MSH6 (mutS homolog 6)
Diseases named in the same sentence as MSH6 in open-access papers (continued):
Sharing a sentence is not in itself a finding about the gene and the disease.
lymphoma (13 papers, 2009 to 2025). A malignant (clonal) proliferation of B- lymphocytes or T- lymphocytes which involves the lymph nodes, bone marrow and/or extranodal sites. "Recently a link between mutations in MSH6 and childhood leukemia/lymphoma was identified." (PMID 21437237, 2011). "In addition, MSH6 and PMS2 tended to be lower in BLV-infected cattle with lymphoma compared within infected cattle." (PMID 33143351, 2020). "Interestingly, AID deficiency reduces the risk for development of Bcl6-dependent germinal center-derived lymphoma, while the loss of AID has no impact on Myc-driven, pre-germinal center lymphomas or on the progression of germinal center-like lymphomas in Msh6-deficient mice." (PMID 24212831, 2011).
thyroid cancer (11 papers, 2015 to 2024). "This analysis revealed that seven of the novel identified variants were located in genes previously associated with thyroid cancer: MSH6, FOXM1, EPCAM, HOOK3, BMP1, TG and NTRK1." (PMID 37175550, 2023). "A recent case–control study comprising 106 thyroid cancer patients and 212 age- and gender-matched controls revealed that MSH6 rs1042821 variant homozygotes exhibited higher risk of this cancer (OR = 3.42, CI = 1.04–11.24, p = 0.04)." (PMID 32756484, 2020). "We also learned that within family BN10, from which two family members were detected with MSH6 G355S in our study, four out of all five sisters suffer from thyroid cancer." (PMID 26530882, 2015).
colon adenocarcinoma (10 papers, 2021 to 2025). "Subject 2 was diagnosed at age 44 with MMRd colon adenocarcinoma with loss of MSH6 staining by IHC." (PMID 36091175, 2022). "We revealed the colon adenocarcinoma patients (COAD) with mutations of a CRs set (EP300, MSH6, NSD2 and TRRAP) mediate a better survival with low expression of MAP2 and could benefit from taxnes." (PMID 36180906, 2022).
lung carcinoma (10 papers, 2011 to 2025). "Patients with mutant genotype (TT) for MSH6 polymorphism have 1.5-fold risk for the development of lung cancer (p = 0.03)." (PMID 39003369, 2024). "For MSH6 (rs3136228) polymorphism, our results suggest an increased susceptibility towards lung cancer in subjects harbouring the GG genotype (AOR 1.43; p = 0.03) when the recessive genetic model was applied." (PMID 39003369, 2024). "The Cox regression model analysis for the MSH6 polymorphism showed a two-fold increase in the hazard ratio and a corresponding poor outcome for these lung cancer patients (HR = 2.28; MST = 4.9; p = 0.03)." (PMID 39003369, 2024). "For MSH6 polymorphism, our data suggest that in the recessive model for non-smokers, the TT genotype was observed to incur a threefold risk of lung cancer development (p = 0.01)." (PMID 39003369, 2024). "MSH3 and MSH6 polymorphisms are involved in modulating the risk towards lung cancer." (PMID 39003369, 2024). "This case–control study focuses on whether MSH3 Ala1045Thr (rs26279) and MSH6 (rs3136228) genetic polymorphisms play any role in modulating the risk for lung cancer." (PMID 39003369, 2024). "In addition, MSH6’s high expression level was also significantly linked to poor FP (First progression) (P=2.3e-09) and OS (P=2.8e-09) in lung cancer patients." (PMID 34941572, 2021). "However, a recent pan-cancer study reported that germline gene mutations in MSH6 were present in ~1% (2/191) of lung cancers patients." (PMID 31297337, 2019). "The present study investigated the relationship between MSH3 and MSH6 genes in lung cancer patients." (PMID 39003369, 2024). "Significant associations with lung cancer and polymorphisms in genes involved in DNA damage sensing (ATM) and, in four genes encoding proteins involved in mismatch repair (LIG1, LIG3,MLH1, and MSH6) found." (PMID 40958859, 2025). "Another well-known risk factor for lung cancer is tobacco smoking; therefore, to evaluate the synergistic role of smoking and MSH3 & MSH6 polymorphisms towards lung cancer susceptibility, we stratified our data based on smoking status to study the gene-environment interaction." (PMID 39003369, 2024). "However, we could not find any study demonstrating any association among MSH6 variants, lung cancer susceptibility and smoking status." (PMID 39003369, 2024). "However, we could not find any study investigating the role of MSH6 polymorphism in the overall survival of lung cancer patients concerning chemotherapy." (PMID 39003369, 2024). "So far as our knowledge is concerned, no study has been evaluated in Indian lung cancer patients to evaluate the role of the MSH3 and MSH6 polymorphism towards lung cancer susceptibility and as a prognostic marker." (PMID 39003369, 2024). "Additionally, the prognosis of lung cancer patients was evaluated based on the genotypes of MSH3 and MSH6, stratified by histological subtypes." (PMID 39003369, 2024).
lung carcinoma (continued). "Analysis indicated that CDKN2A, FAT1, MSH6, ARID1A, KEAP1, NF1, and SMAD4 mutation was more recurrent in patients with ERBB2 SNV/indels within the kinase domain compared with non-kinase domain in lung cancer." (PMID 35911441, 2022).
colorectal adenocarcinoma (9 papers, 2013 to 2025). The most common type of colorectal carcinoma.
colorectal tumors (9 papers, 2004 to 2020). "Five novel MSH6 missense mutations (MSH6-R128L, MSH6-P623L, MSH6-K728T, MSH6-G881K+S, MSH6-E1193K) were found in six patients, whose endometrial or colorectal tumour showed high MSI (when at least two out of five markers showed instability)." (PMID 15354210, 2004). "On the other hand, approximately 5% of colorectal tumours of MSH6 mutation carriers do show neither an MSI-high pattern nor loss of MSH6 expression and thus might have arisen independent from the genetic background of the carrier." (PMID 17117178, 2006). "Data from previous studies show that approximately 15% of colorectal tumours of MSH6 mutation carriers do not have an MSI-high pattern, whereas they do show loss of MSH6 expression and thus might be the result of the MSH6 germline mutation." (PMID 17117178, 2006).
endometrioid carcinoma (9 papers, 2010 to 2025). "For endometrioid carcinoma, ER and progesterone (PR) receptors were observed in 34 and 21% of cases, respectively, and one case of EC with mucinous features had a loss of MSH6 and ARID1A in tumor cells with a positive stain in stromal tissue and lymphocytes." (PMID 32677969, 2020). "Among patients with a high TMB, two patients with endometrioid carcinomas harbored each two variants in the DNA mismatch repair genes MLH1 and MSH6, which is consistent with biallelic inactivation." (PMID 33947352, 2021). "All patients who were MSH6 protein negative were diagnosed with early-stage endometrioid carcinoma (EC), with a median age of 55 years (range 48–67 years)." (PMID 40469174, 2025).
HBOC syndrome (9 papers, 2016 to 2025).
medulloblastoma (9 papers, 2017 to 2025). A malignant, invasive embryonal neoplasm arising from the cerebellum. "No homozygous P/LP variants were observed; however, in addition to the CMMRD patient with compound heterozygous MSH6 variants, a patient with medulloblastoma (MB, PT_2FK75B27) had two adjacent PMS2 P/LP InDels on the same allele, despite no reported CPS." (PMID 39974082, 2025). "With respect to potential genotype–phenotype correlations, it is noteworthy that two MSH6-deficient patients (P2 and P14) had a medulloblastoma." (PMID 30013564, 2018). "MSH6 mutation is associated with the development of medulloblastoma or AML." (PMID 32296698, 2020). "Because six of the ten previously published CMMRD cases with medulloblastoma were also MSH6-deficient, and given that only approximately 20% of CMMRD patients are due to biallelic MSH6 mutations, this suggests an over-representation of medulloblastoma among MSH6-deficient individuals." (PMID 30013564, 2018). "Germline defects in medulloblastoma patients were observed also in other genes cooperated with NBN in BRCA1-associated genome surveillance complex (BASC), including MSH6, PMS2 and MLH1." (PMID 28376765, 2017). "In medulloblastoma patients pathogenic variants in MLH1, MSH6 and PMS2 genes were detected previously." (PMID 28376765, 2017).
(CMMRD) syndrome (8 papers, 2017 to 2025). "The patient was later diagnosed with CMMRD syndrome (mutation in the MSH6 gene)." (PMID 39247025, 2024).
cervical carcinoma (8 papers, 2010 to 2025). A carcinoma arising from either the exocervical squamous epithelium or the endocervical glandular epithelium. "Expression of the MMR proteins MLH-1, PMS-2, MSH-2, and MSH-6 was investigated by immunohistochemical staining in a prospectively collected cervical cancer cohort (n=508) with corresponding clinicopathological and follow-up data." (PMID 38950928, 2024). "In MSI-H cervical cancer, the genomic alteration rates of MSH6 and MLH1 were the highest (n = 4, 30.8%)." (PMID 38201563, 2023). "Genes with known or likely deleterious variants among cervical cancer patients with DDR gene alterations were ATM (n = 3, 2.33%), BRCA2 (n = 3, 2.33%), ATR (n = 2, 1.55%), CHEK2 (n = 2, 1.55%), followed by BRCA1 (n = 1, 0.78%), FANCA (n = 1, 0.78%), MSH6 (n = 1, 0.78%), and RAD51D (n = 1, 0.78%)." (PMID 35071000, 2021). "In addition, other genes associated with cervical cancer, including MSH6, were negative." (PMID 39080663, 2024).
Cowden syndrome (7 papers, 2013 to 2024). "However, the patients did not present typical clinical phenotypes; in the case of the MSH6 variant the tumor did not display microsatellite instability and in the case of the PTEN variant patient records revealed no features suggestive of Cowden syndrome (MIM 158350)." (PMID 24146633, 2013).
gynecological cancers (7 papers, 2018 to 2025). "It is worth mentioning that our series also includes 85 female carriers of a mutation in the MSH6 gene, 32 of whom (37.6%) developed gynecological cancer (24 EC, 5 OC and 3 synchronous EC and OC), all from the non-RRGS group." (PMID 33218006, 2020). "Among prospectively detected BC or gynecological cancer phenocopies in the path_BRCA1/2 families, we found that 4/48 have pathogenic variants in high-penetrance cancer genes: two BC- and one CRC-associated gene (ATM, BRCA2 and MSH6, respectively)." (PMID 29371908, 2018). "However, the number of gynecological cancers in females carrying an MSH6 mutation were lower than expected, probably because most of our patients were identified by clinical criteria (Amsterdam and Bethesda), which are focused mainly on CRC, which is less frequent than EC in MSH6 carriers." (PMID 33218006, 2020).
Muir-Torre syndrome (7 papers, 2012 to 2025). Muir-Torre syndrome (MTS) is a form of hereditary nonpolyposis colon cancer (HNPCC) characterized by cutaneous sebaceous tumors, keratoacanthomas and at least one visceral malignancy, most frequently gastrointestinal carcinoma.